SOX4 (SRY-box transcription factor 4)
Diseases named in the same sentence as SOX4 in open-access papers (continued):
Sharing a sentence is not in itself a finding about the gene and the disease.
breast carcinoma (continued). "Immunohistochemical analysis of SOX4 expression in patients with human breast cancer reveals a positive correlation with decreased survival, increased metastasis and elevated blood vessel density." (PMID 30507376, 2018). "(G) Analysis of the prognostic value of the core-SOX4 gene expression signature (650 genes) in claudinlow breast cancer patients (METABRIC)." (PMID 30507376, 2018). "Stratification of patients with breast cancer according to the ER-status revealed that patients with high levels of SOX4 have a significantly worse prognosis in the ER-positive tumor group, and a trend towards poor-prognosis in the ER-negative tumor group." (PMID 30507376, 2018). "As a driver of both EMT and tumor-induced angiogenesis, SOX4 is an interesting therapeutic target in breast cancer, allowing for the simultaneous inhibition of multiple biological processes required for tumor metastasis." (PMID 30507376, 2018). "An important finding is that the SOX4 core-signature is strongly predictive for survival specifically in the Claudinlow breast cancer subtype." (PMID 30507376, 2018). "The context dependent nature of SOX4 transcriptional networks is of particular importance in heterogeneous diseases such as breast cancer." (PMID 30507376, 2018). "Accordingly, high levels of SOX4 expression significantly correlated with decreased overall survival in breast cancer patients, and this was also observed when patients were subdivided into the major subtypes ILC and IDC." (PMID 30507376, 2018). "Breast cancer studies have suggested that SOX4 induces epithelial-to-mesenchymal transition (EMT) and cooperates with the RAS oncogene in cancer progression." (PMID 30072631, 2018). "Firstly, using gene expression files, we found that the expression of SOX7, SOX17 and SOX18 was significantly reduced, whereas SOX4 was markedly increased in breast cancer tissues compared to normal tissues." (PMID 27188720, 2016). "Recently, we found that TCDD suppresses invasion of breast cancer cells by inducing the Sox4-targeting miR-212/132 cluster." (PMID 27907195, 2016). "EMT studies in breast cancer have indicated that, similar to the pancreatic cancer example, TGFβ-induced Sox4 expression positively contributed to the EMT and cell survival." (PMID 27367735, 2016). "Overexpression of Sox-4 in Flavipin-treated cells mitigated the inhibitory effects of Flavipin on breast cancer migration and invasion." (PMID 27907195, 2016). "miRNAs, such as miR-335, are known to target SOX4, suppressing metastasis and migration in breast cancer." (PMID 25644061, 2015). "For instance, the miRNA miR-335-5p, the top hub node in the network is already known to be a key regulator in suppressing breast cancer metastasis and migration through regulation of targets SOX4 and TNC." (PMID 26763900, 2015). "It has been reported that miR-335 suppresses breast cancer metastasis by targeting SOX4 and Tenascin C, small cell lung cancer metastasis by targeting IGF1R and RANKL, and induces apoptosis of breast cancer cells by regulating ERα, IGF1R, SP1, and ID4." (PMID 26098312, 2015). "High SOX4 expression has been shown to affect tumor development or progression in gastric cancer, colon cancer, prostate cancer, breast cancer, lung cancer, and endometrial cancer." (PMID 26555193, 2015). "Taken together, the results identified SOX4 as a new target gene of the miR-212/132 cluster in human breast cancer cells." (PMID 26377202, 2015). "The TCDD- and DIM-mediated inhibition of breast cancer cell migration, expansion and invasion was moderately abrogated by SOX4 over-expression." (PMID 26377202, 2015). "SOX4 has been demonstrated to be highly expressed in breast cancer, lung cancer, glioma, prostate cancer, and gastric cancer." (PMID 26578818, 2015). "Cluster I showed overexpression of the lncRNAs that influence their neighboring genes, ALDH1A3 (a breast cancer stem cell marker), SOX4, SOX9, and VIM." (PMID 25296969, 2014).
breast carcinoma (continued). "SOX4 is a transcription factor regulated by progesterone in breast cancer cells, and was identified as an oncogene in prostate cancer." (PMID 23758962, 2013). "SOX4 has also been demonstrated to contribute to cancer progression and metastasis in breast cancer glioma and HCC." (PMID 23301048, 2013). "Of these, miR-335 was reported to suppress metastasis and migration by targeting SOX4 and tenascin C and inhibit tumor initiation in breast cancer." (PMID 23229728, 2013). "This group of genes included three transcriptional activators PBX1, SOX4 and ETS2, which have been linked to breast cancer tumorigenesis." (PMID 23301048, 2013). "We have discovered that junction plakoglobin (JUP) interacts with SOX4 in both the cytosol and the nucleus and the interaction between SOX4 and plakoglobin is significantly increased when prostate and breast cancer cells are stimulated with WNT3A." (PMID 22098624, 2011). "Recently, both SOX4 and tenascin C were shown to enhance metastasis of breast cancer cells to the lung." (PMID 20419098, 2010). "The SOX4 gene is highly expressed in human breast cancer cell lines, colon cancer cell lines, hepatocarcinoma, medulloblastomas, and adenoid cystic carcinomas." (PMID 18498649, 2008). "Sox4 is expressed in pancreatic cells, lung cancer, breast cancer, and hepatocellular carcinoma." (PMID 40980324, 2025). "Moreover, substantial evidence shows that Met can exert its effects by inhibiting the expression of SOX4, thereby inhibiting the progression of diseases such as breast cancer, lung cancer, and atherosclerosis." (PMID 40595502, 2025). "It is reported that after Sox4 expression of breast cancer cells is knocked down by siRNA, Wnt/β-catenin signaling is also observed to be synchronously inhibited through feedback loop, and subsequently, EMT, CSC-like features and cisplatin resistance are reversed." (PMID 41211430, 2025). "Accordingly, the inhibition of NF-κB blocks CXCL1-induced SOX4 overexpression, increases the E-cadherin and reduces both vimentin and β-catenin expression, underlying the importance of CXCL1/SOX4/NF-κB axis in sustaining breast cancer." (PMID 38397187, 2024). "In addition, the study indicated that the protein expression of SOX4 was significantly higher in breast cancer, LUAD, and UCEC." (PMID 37958409, 2023). "Indeed, other groups have shown that SOX4 overexpression induces EMT in breast cancer cells, which in turn upregulates stem cell markers and enhances mammosphere formation." (PMID 36766786, 2023). "Moreover, we performed a protein expression analysis of SOX4 for breast cancer, colon cancer, ovarian cancer, clear cell renal cell carcinoma, UCEC, LUAD, and pediatric brain cancer using the “CPTAC analysis” module of UALCAN." (PMID 37958409, 2023). "In addition, SOX4 is closely related to the multidrug resistance of lung cancer, colon cancer, breast cancer, leukemia, and other malignant tumors." (PMID 37958409, 2023). "Moreover, SOX4 can promote the growth and metastasis of breast carcinoma and has been proposed as a biomarker of poor prognosis in breast carcinoma patients." (PMID 37468850, 2023). "Furthermore, in colorectal and breast cancer, SOX4 expression is dysregulated, in part, by a reduced expression of miR-129-5p." (PMID 37375678, 2023). "A targeting relationship between miR-1225-3p and SOX4 in breast cancer is identified." (PMID 35112991, 2022). "Notably, high SOX4 expression level was found to be significantly correlated with triple-negative breast cancer, breast cancer metastasis, as well as gastric cancer." (PMID 34708244, 2022). "Circ_0000518, miR-1225-3p and SOX4 form a ceRNA network to promote breast cancer progression." (PMID 35112991, 2022). "In addition, the knockdown of H19 suppresses cell growth by attenuating miR-138-mediated SRY-box transcription factor 4 (SOX4) suppression in breast cancer." (PMID 36613528, 2022). "MEM2 is transcriptionally activated by SOX4 in breast cancer." (PMID 35294319, 2022).
breast carcinoma (continued). "Many lncRNAs act as promoters or suppressors in tumors, for example, LncRNA-42060 regulates the miR-204-5p/SOX4 axis in canine mammary tumor cells by regulating tumor development, and in this process, lncRNA-42060 promotes the development of canine mammary tumors." (PMID 35202335, 2022). "The pro-oncogenic function of SOX4 in breast cancer is widely attributed to its ability to modulate epithelial-to-mesenchymal transition (EMT), activation of multiple pro-proliferative or pro-survival signaling pathways, increased angiogenesis as well as its role in regulating cancer cell stemness." (PMID 33837205, 2021). "The relationship between SOX4 and miR-30a was analyzed through breast cancer TCGA database (n=973)." (PMID 34234874, 2021). "To examine whether the repression of SOX4 by miR-30a mediated EMT and CSC inhibition, we studied the EMT and CSC phenotypes of breast cancer cells following SOX4 knockdown with shRNA." (PMID 34234874, 2021). "This is supported by the findings that the SOX4-dependent genes in PyMT tumor-organoids strongly overlap with genes correlating with SOX4 in human mammary tumors in the TCGA and METABRIC studies and the previously published correlation of SOX4 and mitotic index in breast cancer patients." (PMID 34584219, 2021). "Previous studies have shown that SOX4 expression is upregulated in breast cancer 9 and promotes HCC metastases 14, suggesting it might lead to poor metastasis-free survival." (PMID 33995626, 2021). "An increasing number of studies attest to an important role for SOX4 in breast cancer." (PMID 34584219, 2021). "A recent study showed that SOX4 also played a role in angiogenesis of breast cancer." (PMID 34047469, 2021). "In contrast, genes often associated with the basal-like subtype and a poor prognosis such as MCL1, CTNNB1, EGFR, or SOX4 were found in the basal-like patient GSM519217 suggesting that the generated networks are capable of extracting breast cancer subtype-specific features." (PMID 33706810, 2021). "Considering the reciprocal expression patterns of miR-30a and SOX4 in breast cancer samples, feedback circuit could exist between miR-30a and SOX4." (PMID 34234874, 2021). "To interrogate whether these findings recapitulated the role of SOX4 in human mammary tumors, we used the cbioportal resource." (PMID 34584219, 2021). "Our results indicated that SOX4/CXCR7 axis plays important roles in breast cancer and may serve as potential novel therapeutic targets in the treatment of this disease." (PMID 33005101, 2020). "In conclusion, our study revealed that SOX4 promotes the growth and metastasis of breast cancer." (PMID 33005101, 2020). "One of the important findings in this study is that ectopic expression of SOX4 increases the susceptibility of breast cancer cells to paclitaxel, suggestive of the potential use of paclitaxel in breast cancer treatment if the expression level of SOX4 in the tumor is high." (PMID 33005101, 2020). "Moreover, CXCL1 silencing in TAMs was found to inhibit breast cancer growth and lung metastasis via inhibiting NF-κB/SOX4 signaling in both murine and human models." (PMID 32213179, 2020). "Recently, SOX4 was reported to promote epithelial-mesenchymal transition (EMT) in breast cancer." (PMID 33005101, 2020). "SOX4 plays an important role in the growth and metastasis of breast cancer." (PMID 33005101, 2020). "Moreover, rescue experiments further confirmed that LINC01133 functional acted as an anti‐oncogene, at least partly, via repressing SOX4 in breast cancer." (PMID 31557401, 2019). "For instance, activated SOX4 signaling was reported to promote breast cancer metastasis." (PMID 30922402, 2019). "The inhibition role of LINC01133 on breast cancer invasion and metastasis may partly through restraining SOX4 transcription by binding with EZH2." (PMID 31557401, 2019).
breast carcinoma (continued). "To further determine potential targets of LINC01133 involved in breast cancer invasion and metastasis, we investigate the expression of metastatic regulators and found that both mRNA level and protein level of SOX4 was significantly increased in response to LINC01133 knockdown." (PMID 31557401, 2019). "Furthermore, we confirmed that the oncogenic effect of LINC01133 knockdown on breast cancer cells is at least partly dependent on the negative regulation of SOX4." (PMID 31557401, 2019). "Using a combination of in vitro experiments utilizing multiple epithelial-derived breast cell lines, in vivo animal models, and analysis of patient tumor samples, we show that SOX4-mediated transcriptional regulation can affect breast cancer progression by promoting tumor-induced angiogenesis." (PMID 30507376, 2018). "(H) Schematic model for the pro-angiogenic function of SOX4 during breast cancer progression." (PMID 30507376, 2018). "Furthermore, in breast tumors, SOX4 expression correlates with blood vessel density and size, and predicts poor-prognosis in patients with breast cancer." (PMID 30507376, 2018). "When CXCL1 was overexpressed in breast cancer cells, SOX4 expression was concomitantly increased." (PMID 30158589, 2018). "The results of this study showed that CXCL1 was the most significant cytokine derived from TAMs for inducing breast cancer metastasis, suggesting that the NF-κB/SOX4 pathway may be involved in downstream signaling." (PMID 30158589, 2018). "Despite our finding that EDN1 was one of the few genes commonly regulated by SOX4 in the different breast epithelial cell lines used in this study, future work will have to uncover whether this regulation is conserved in all breast cancer cells and subtypes." (PMID 30507376, 2018). "Despite these observations, the transcriptional network and molecular mechanisms through which SOX4 contributes to the pathogenesis of breast cancer remain largely unknown." (PMID 30507376, 2018). "In agreement with the observation that SOX4 transcriptional networks are context-dependent and directed in part by the epigenome, we observed that SOX4-target genes strongly correlated with decreased survival only in Claudinlow breast cancers." (PMID 30507376, 2018). "Our in vitro and in vivo experiments demonstrate a novel pro-oncogenic function of SOX4 in mammary tumor development as a promoter of tumor-induced angiogenesis, and furthermore we show that SOX4-high breast tumors are highly vascularized, aggressive and therapy-resistant." (PMID 30507376, 2018). "A number of studies have indicated a role for SOX4 in mammary tumor progression." (PMID 30507376, 2018). "Similarly to NEK7, SOX4 has been identified as an important oncogene in a variety of other cancers including endometrial cancer, brain cancer, breast cancer, bladder cancer, ovarian cancer, colorectal cancer, liver cancer and leukemia." (PMID 27115612, 2016). "Therefore, Sox4 most likely contributed to the suppressive effects on Flavipin on motility of the breast cancer cells." (PMID 27907195, 2016). "In contrast, SOX4 was markedly increased in breast cancer tissues." (PMID 27188720, 2016). "It significantly increases junction plakoglobin, interacts with sex-determining region Y-related high-mobility group box 4 (SOX4) in both the cytosol and the nucleus, and enhances the interaction between SOX4 and plakoglobin in prostate and breast cancer cells." (PMID 26369691, 2015). "In addition, the role of SOX4 in mediating the inhibitory effects of Ahr agonists on migration, expansion and invasion of breast cancer cells was confirmed by over-expression of SOX4." (PMID 26377202, 2015).
breast carcinoma (continued). "In its turn, MIR-191 downregulates large set of genes including SOX4 in breast cancer." (PMID 25329802, 2014). "Moreover, in patient breast cancer samples SOX4 expression correlated with tumor-grade and triple negative breast cancers." (PMID 23301048, 2013). "It is thus possible that similar to glioma, TGF-β-induced breast cancer stem cells properties are mediated by SOX4, suggesting that SOX4 induction might impact on multiple aspects of the EMT phenotype." (PMID 23301048, 2013). "SOX4 could affect epithelial–mesenchymal transition in prostate, gastric, and breast cancers." (PMID 37251541, 2023). "Furthermore, miR-381-3p could bind to the 3′-UTR of both Sox4 and Twist1, suggesting that miR-381-3p inhibits breast cancer EMT by targeting Sox4 and Twist1." (PMID 34362391, 2021). "Moreover, Hanieh, (2015; 2016) assessed the AhR-miR-212/132 axis in breast cancer cell lines and confirmed the anti-metastatic properties of the miRNA cluster through suppression of SOX-4, which inversely is a pro-metastatic factor and has binding sites for miR-212/132 on the 3′ UTR region." (PMID 34746229, 2021). "SOX4/CXCR7 may serve as potential therapeutic targets for the treatment of breast cancer." (PMID 33005101, 2020). "Taken together our integrative genome-wide analysis of the SOX4 transcriptional network has uncovered a novel role for SOX4 in tumor-induced angiogenesis in vitro and in vivo as well as in breast tumors, revealing a novel mechanism by which SOX4 may contribute to breast cancer metastasis." (PMID 30507376, 2018). "Interestingly, SOX4 expression is also increased in normal mammary stem cells, and together with other mammary stem cells markers identifies the cancer stem cell content of breast cancers." (PMID 23301048, 2013). "By negatively regulating the expression of SOX4, miR-129-5p significantly reduces the IC50 of several drugs, including adriamycin, which proves that breast cancer cells are more sensitive to drugs." (PMID 41211430, 2025). "Engagement of Sox4 in alternative transcriptional programs involves Sox4 upregulation and reorganization of TF landscapes by TGF-β signaling in pancreatic and mammary cancer cells." (PMID 40393982, 2025). "SOX4 overexpression partially blocked TCDD and MCDF-mediated inhibition of breast cancer cell (MDA-MB-231) migration and invasion in line with the oncogenic role of SOX4." (PMID 37696456, 2023). "lncRNA-ARNILA, as a competitive endogenous RNA (ceRNA) for miR-204, promotes the expression of its target gene Sox4, induces EMT and promotes breast cancer progression." (PMID 36450882, 2022). "Consistently, by suppressing SRY-box transcription factor 4 (SOX4) expression, LINC01133 is capable of inhibiting metastasis in breast cancer." (PMID 35055115, 2022). "AhR–dependent mechanisms for the inhibition of breast cancer by AhR agonists are variable and include the downregulation of multiple genes/gene products such as CXCR4, MMPs, CXCL12, SOX4 and the modulation of microRNA levels." (PMID 36428667, 2022). "MiR-320d was also downregulated in breast cancer tissues and can be used as an independent predictor of prognosis in breast cancer, miR-320d and HNF1A-AS1 competitively bind SOX4 to inhibit the progression of breast cancer." (PMID 36591520, 2022). "The effects of miR-30a and target gene SOX4 on EMT and CSC phenotypes in breast cancer were explored in vitro and in vivo." (PMID 34234874, 2021). "Altogether, these results indicated that suppression of SOX4 was required for miR-30a mediated inhibition of EMT and CSC phenotypes in breast cancer cells." (PMID 34234874, 2021). "miR-381-3p inhibits breast cancer progression and EMT by regulating the TGF-β signaling via targeting Sox4 and Twist1." (PMID 34362391, 2021). "Our observation suggests that miR-381-3p inhibits breast cancer progression and EMT by regulating the TGF-β signaling via targeting Sox4 and Twist1." (PMID 34362391, 2021).